MPZL1 (myelin protein zero like 1)
Description:
Cell surface receptor, which is involved in signal transduction processes. Recruits PTPN11/SHP-2 to the cell membrane and is a putative substrate of PTPN11/SHP-2. Is a major receptor for concanavalin-A (ConA) and is involved in cellular signaling induced by ConA, which probably includes Src family tyrosine-protein kinases. Isoform 3 seems to have a dominant negative role; it blocks tyrosine phosphorylation of MPZL1 induced by ConA. Isoform 1, but not isoform 2 and isoform 3, may be involved in regulation of integrin-mediated cell motility.
Synonyms: PZR; FLJ21047; MPZL1b; PZR1b; PZRa; PZRb
Tractability: Antibody: its Gene Ontology location is reachable by antibodies, with high confidence; UniProt predicts a signal peptide or a membrane-spanning region; the Human Protein Atlas places it where antibodies can reach. PROTAC: ubiquitination databases record sites on it; its protein half-life has been measured.
Gene: Protein-coding gene on chromosome 1 (167,721,192 to 167,791,919, forward strand). Ensembl gene ENSG00000197965.
Subcellular location: Membrane
Subcellular location (Human Protein Atlas): Plasma membrane; Vesicles
Gene Ontology:
Molecular function: identical protein binding; protein binding; structural molecule activity
Biological process: cell surface receptor protein tyrosine kinase signaling pathway; cell-cell signaling
Cellular component: cell surface; focal adhesion; plasma membrane; membrane
Genetic constraint (gnomAD): Loss-of-function variants: 12 observed, 25.03 expected, observed/expected ratio (o/e) 0.48, 90% interval 0.31 to 0.78. The upper end of that interval is the gene's LOEUF score, 0.78, which puts it in group 3 of 6, group 1 being the genes least tolerant of losing a copy. Missense variants: 272 observed, 318.59 expected, observed/expected ratio (o/e) 0.85, 90% interval 0.77 to 0.94. Synonymous variants: 140 observed, 129.46 expected, observed/expected ratio (o/e) 1.08, 90% interval 0.94 to 1.24.
Homologues: Orthologues: chimpanzee MPZL1 (99% identical), macaque MPZL1 (98% identical), dog MPZL1 (93% identical), rabbit MPZL1 (92% identical), guinea pig MPZL1 (88% identical), mouse Mpzl1 (83% identical), rat Mpzl1 (83% identical), pig MPZL1 (68% identical), tropical clawed frog mpzl1 (48% identical), zebrafish mpzl1l (41% identical). Paralogues in human: MPZ (33% identical), MPZL3 (24% identical), MPZL2 (23% identical), JAML (20% identical), SCN4B (19% identical), SCN2B (18% identical).
Diseases named in the same sentence as MPZL1 in open-access papers:
MPZL1 is named in the same sentence as 34 diseases in open-access papers, as found by Europe PMC text mining. Sharing a sentence is not in itself a finding about the gene and the disease. The quoted sentences say what the papers report.
hepatocellular carcinoma (6 papers, 2017 to 2025). A malignant tumor that arises from hepatocytes. "In hepatocellular carcinoma, MPZL1 recruits SHP-2 to phosphorylate Src kinase at Tyr426, subsequently leading to cortactin phosphorylation, which promotes the migration of hepatocellular carcinoma cells." (PMID 40223054, 2025). "MPZL1 was a transmembrane glycoprotein that promoted migration of hepatocellular carcinoma cells and was involved in extracellular matrix‐induced signal transduction." (PMID 39810466, 2025). "On BTA3, the MPZL1 (myelin protein zero like 1) gene could significantly enhance the migratory and metastatic potential of hepatocellular carcinoma cells by phosphorylating and activating the pro-metastatic protein." (PMID 32171250, 2020).
glioblastoma (3 papers, 2024). The most malignant astrocytic tumor (WHO grade IV). "Other genes hypomethylated and overexpressed in PTCL - RAB13, MPZL1, CDK14- were implicated in tumor progression of several different tumors including B-cell lymphomas, and glioblastomas, lung and ovarian." (PMID 38464090, 2024).
glioma (3 papers, 2024 to 2025). A benign or malignant brain and spinal cord tumor that arises from glial cells (astrocytes, oligodendrocytes, ependymal cells). "Further survival analysis showed that high MPZL1 expression was strongly associated with a poor prognosis in glioma patients (Kaplan Meier, P < 0.05)." (PMID 38882007, 2024). "We further show that this AS signature can be regulated by mutant EGFR or IDH1 and elucidate the functional mechanisms of AS events in genes CERS5 and MPZL1 in promoting glioma malignancy." (PMID 38662454, 2024). "Additionally, MPZL1 is highly expressed in various cancers, such as lung cancer, glioma, ovarian cancer, and gallbladder cancer." (PMID 40223054, 2025). "AS of CERS5 and MPZL1 influences the oncogenic potential of glioma cells." (PMID 38662454, 2024). "Moreover, Western blotting assays showed that the amount of MPZL1 protein was significantly up-regulated in glioma tissues compared with the normal (one-way ANOVA, P < 0.01)." (PMID 38882007, 2024).
ovarian carcinoma (3 papers, 2023 to 2025). A malignant neoplasm originating from the surface ovarian epithelium. "Similarly, Chen reported that elevated expression of MPZL1 stimulates the phosphorylation of Src kinase, facilitating the proliferation and migration of ovarian cancer cells." (PMID 38562930, 2024).
leukemia (2 papers, 2024). A malignant (clonal) hematologic disorder, involving hematopoietic stem cells and characterized by the presence of primitive or atypical myeloid or lymphoid cells in the bone marrow and the blood. "Several genes from this group, such as UHRF1, MPZL1, CDK14, RACGAP1, RAB13, and others have oncogenic functions in various solid tumors, leukemias, and lymphomas either predicting poor prognosis, involved in tumor migration, metastasis, or maintenance." (PMID 38464090, 2024).
lung adenocarcinoma (2 papers, 2023 to 2025). A carcinoma that arises from the lung and is characterized by the presence of malignant glandular epithelial cells. "MPZL1 can bind with β1 transforming growth factor to promote the development of lung adenocarcinoma." (PMID 40223054, 2025). "The upregulation of MPZL1 in lung adenocarcinoma negatively regulates the infiltration of CD8 + T cells, which is associated with resistance to immunotherapy." (PMID 40223054, 2025). "However, in another study, MPZL1 was found to inhibit the proliferation, metastasis, invasion, and cancer stem cell characteristics of lung adenocarcinoma by activating the β-catenin/TCF-4 signaling pathway, highlighting the complex role of MPZL1 in tumor development." (PMID 40223054, 2025).
lymphoma (2 papers, 2024). A malignant (clonal) proliferation of B- lymphocytes or T- lymphocytes which involves the lymph nodes, bone marrow and/or extranodal sites. "For example, MPZL1 and UCK2 loci uniformly hypermethylated in normal T-cells were hypomethylated in lymphomas with high frequency." (PMID 38464090, 2024).
bladder cancers (1 paper, 2024). "Furthermore, the biological impact of MPZL1 in diverse tumors, including ovarian, colorectal, and bladder cancers, has been investigated and corroborated, highlighting its promotional influence on tumor progression." (PMID 38562930, 2024).
breast carcinoma (1 paper, 2017). "In addition to MPZL1, a few other novel GRB2-associated proteins that we identified in our MS experiments were linked with breast cancer." (PMID 28912526, 2017). "To examine the requirement for PTPN11 in complex formation in HER2+ breast cancer cells, we analyzed GRB2 and MPZL1 localization in cells depleted of PTPN11." (PMID 28912526, 2017). "The importance of MPZL1 for GRB2-PTPN11 localization in cells adhering to fibronectin, as well as its requirement for the activation of oncogenic signalling downstream of GRB2 in the context of HER2+ breast cancer are key questions that will need to be addressed." (PMID 28912526, 2017).
colon cancer (1 paper, 2025). "High GAST (which encodes PG) and MPZL1 transcript levels in primary colon cancer patients is predictive of worse prognosis." (PMID 40753649, 2025).
hypertrophic cardiomyopathy (1 paper, 2025). A condition in which the myocardium is hypertrophied without an obvious cause. "Many NSML mutations result in low or no catalytic activity but also cause large conformational changes that enhance binding to MPZL1/Pzr, a driver of hypertrophic cardiomyopathy through the Akt and NF-κB pathways." (PMID 40631144, 2025).
mesothelioma (1 paper, 2025). A usually malignant and aggressive neoplasm of the mesothelium which is often associated with exposure to asbestos. "By intersecting high-risk genes with upregulated DEGs, we identified four key high-risk genes associated with mesothelioma: MPZL1, SOAT1, TACC3, and CYBRD1." (PMID 40223054, 2025). "In this study, we identified the MPZL1 gene as one of the core genes with a strong causal association with mesothelioma." (PMID 40223054, 2025).
Noonan syndrome (1 paper, 2025). Noonan Syndrome (NS) is characterized by short stature, typical facial dysmorphism and congenital heart defects. "The Noonan Syndrome mutant SHP2T42A enhances intrinsic phosphoprotein binding affinity and alters binding specificity, increasing its interaction with the cell surface receptor MPZL1." (PMID 40661614, 2025).
schizophrenia (1 paper, 2009). A major psychotic disorder characterized by abnormalities in the perception or expression of reality. "Strikingly, the one gene that had previously been found upregulated in schizophrenia, MPZL1, was significantly negatively correlated with the template i.e. expressed at relatively low levels during adolescence." (PMID 19457239, 2009).
viral infections (1 paper, 2020). "We confirmed variants with putative driver role of MAP10, MPZL1, RPS6KA1, SETD1B, TAOK2, TMEM127, and TNFRSF1A genes, and of genes linked to viral infections (DDX3X and RSF1) and DNA repair (PAXIP1)." (PMID 32321919, 2020).
tumor (15 papers, 2016 to 2025). "We also postulate that MPZL1 is intricately linked to the proliferation and migration of ccRCCs, exerting inhibitory effects on the immune microenvironment of tumors, thereby contributing to tumor progression or recurrence." (PMID 38562930, 2024). "Through an exploration of cellular interactions, we discovered that the MPZ signaling pathway network exhibits substantial cellular interactions in crucial subpopulations of Myofibroblasts and tumor cells, with the gene MPZL1 identified as a key player." (PMID 38562930, 2024). "Although MPZL1 is overexpressed in malignant tumor tissues, MPZL1 expression and its relationship with HCC prognosis and recurrence have not been evaluated." (PMID 35205612, 2022). "Finally, experimental validation revealed that the knockout of the key gene within the MPZ pathway, MPZL1, can inhibit tumor activity, proliferation, invasion, and migration capabilities." (PMID 38562930, 2024). "The tumor promoting function of T-AS1 is at least in part depending on MPZL1 expression." (PMID 35637954, 2022). "Knockdown of MPZL1 could abrogate the effect of T-AS1 in the tumor-promoting function." (PMID 35637954, 2022). "MPZL1 mRNA expression was significantly higher in GC tumor tissues compared to adjacent normal tissues of paired samples (n = 27, P < 0.0001); and in GC tumor tissues compared to normal gastric tissues of unpaired samples (Normal, n = 32; Tumor, n = 375; P < 0.0001)." (PMID 35637954, 2022). "We then assessed whether the tumor-promoting function of T-AS1 in GC depends on MPZL1." (PMID 35637954, 2022). "We also found that putative tumor suppressors, such as FOXP1, STK4, and ATM were frequently hypermethylated and silenced whereas oncogenes, such as UHRF1, MPZL1, CDK14, RACGAP1, and RAB13, were hypomethylated and overexpressed suggesting that DNA methylation changes contribute to PTCL development." (PMID 38464090, 2024). "In addition, CLDN18 also correlated significantly with markers of activated CD8 + T cells such as MPZL1, CSE1L, CD37, AHSA1, CD3D and IL2RB, after adjusting for tumor purity." (PMID 37438735, 2023). "In terms of clinicopathological correlation, CETN2, MPZL1, RACGAP1, and SNRPB were upregulated in patients with microvascular invasion, and the expression of MPZL1 and SNRPB was increased in proportion to the Edmonson tumor differentiation grade." (PMID 35205612, 2022). "Our findings indicated an up-regulation of Mpzl1 expression in CD4+ T cells and CD8+ T cells within the spleens of Ddx21MT-immunized mice, suggesting a potential role for high Mpzl1 expression in T cell migration to tumor sites, thereby contributing to anti-tumor immunity." (PMID 39981234, 2025).
cancer (9 papers, 2018 to 2025). A tumor composed of atypical neoplastic, often pleomorphic cells that invade other tissues. "Meanwhile, cell adhesion-associated genes, such as MPZL1, PVRL1, and CLDN7, were also elevated by α-TOS exposure, indicating their decreased cancer metastasis ability." (PMID 29435127, 2018). "MPZL1 was identified as a binding protein of tyrosine phosphatase SHP2 and has been demonstrated to be upregulated in various cancers and promote cell proliferation and migration." (PMID 38662454, 2024). "Among the five genes, the mechanism of HMGA1, MPZL1, RACGAP1, and SNRPB in cancer progression were reported in several prior studies." (PMID 35205612, 2022). "Additionally, the gene targets of these miRNAs included several cancer driver genes including ZNF704 (targeted by ten miRNAs), MMP16 (targeted by eight miRNAs), and KCNN3, POU2F1, ADARB1, MPZL1, RUNX1T1, UBE2W, and DYRK1A genes (targeted by seven miRNAs)." (PMID 37685851, 2023).
MPZL1 also shares sentences with these, for which no sentence is quoted: lung carcinoma (3 papers); B-cell lymphomas (2); gallbladder carcinoma (2); adenoma (1); brain tumor (1); cardiomyopathy (1); chronic lymphocytic leukemia (1); chronic myeloid leukemia (1); colorectal cancer (1); dementia (1); gastric cancer (1); intestinal tumors (1); LEOPARD syndrome (1); lung squamous cell carcinoma (1); Parkinson’s (1); Stroke (1); thyroid cancer (1).